AR (androgen receptor)
Diseases named in the same sentence as AR in open-access papers (continued):
Sharing a sentence is not in itself a finding about the gene and the disease.
prostate carcinoma (continued). "Immunohistochemistry (IHC) showed a significant increase in the percentage of Ki-67 positive proliferating cells in Kmt2cSET∆/∆ prostates and clusters of cells highly positive for AR expression, the primary driver of prostate cancer initiation and progression." (PMID 35354467, 2022). "The androgen receptor also plays a key role in the development of prostate cancer and is also believed to be involved in the excessive proliferation of prostate cells observed during the development of BPH." (PMID 35055079, 2022). "Progression of prostate cancer is driven by the nuclear hormone transcription factor, androgen receptor (AR)." (PMID 35708495, 2022). "It has been shown that iCRT3 can disrupt the interaction between AR and β-catenin and inhibit AR-mediated transcription and cell growth in prostate cancer cells." (PMID 36323713, 2022). "KLK3 eRNAs can also enhance androgen receptor‐dependent gene expression in trans in human prostate cancer." (PMID 35170113, 2022). "The major signaling pathways that are most frequently altered in prostate cancer include androgen receptor (AR), the PI3K, Ras/Raf/MEK/ERK; and the retinoblastoma (RB) signaling pathway." (PMID 35406634, 2022). "For example, sumoylation of AR suppresses its transcriptional activity, and overexpression of SENP1 in prostate cancer enhances AR transcriptional activity, promoting cancer progression and metastasis." (PMID 36284084, 2022). "The impact of environmental hypoxia in modulating the sensitivity to enzalutamide was investigated using a panel of AR-expressing prostate cancer cell lines." (PMID 35302608, 2022). "The CRL4DDB2 ubiquitin ligase inhibits the growth of prostate cancer cells by inducing AR polyubiquitination." (PMID 35813480, 2022). "In particular, they are enriched explicitly in cell lines from estrogen receptor (ER) positive breast cancer and androgen receptor (AR) positive prostate cancers." (PMID 35322869, 2022). "Almost all treatments target androgen metabolism pathways and AR, from castration-sensitive prostate cancer (CSPC) to castration-resistant prostate cancer (CRPC)." (PMID 36362304, 2022). "Of note, the gene encoding the E3 ubiquitin ligase substrate-binding adaptor SPOP is frequently mutated in primary prostate cancer that leads to accumulations of multiple onco-proteins, including BRD4, AR, NANOG, Caprin1, or GLI." (PMID 36357379, 2022). "TR3 overexpression alters AR expression, splicing process, and transactivation towards increasing the androgen independence of AR signaling in prostate cancer cells." (PMID 35454821, 2022). "Aberrant AR signaling is also one of the major reasons for prostate cancer occurrence and progression." (PMID 35630591, 2022). "Androgen receptors (AR) are steroid receptors in the nuclear receptor superfamily and are highly expressed in prostate cancer cells, which play an important role in prostatic hyperplasia and growth." (PMID 36046733, 2022). "In combination, these data generally support the concept that the presence of AR in CAFs exerts a tumor suppressive effect during early, hormone-naïve stages of prostate cancer." (PMID 36671452, 2022). "In prostate cancer, Hsp90 inhibitors promote the degradation of AR to inhibit the oncogenic activity of AR." (PMID 35326427, 2022). "Androgen deprivation therapy (ADT) is another strategy for the treatment of prostate cancer that suppresses serum testosterone to castration levels, thereby preventing AR activation and blocking AR-mediated transcription." (PMID 36209184, 2022). "For example, genomic alterations in c-MYC, FOXO1 or the androgen receptor (AR) have been described in neuroblastoma, breast, and prostate cancer, respectively." (PMID 35242765, 2022). "As early as the 1990s, HSP70s were isolated and purified from the AR heterocomplex in LNCaP cells, showing that HSP70s are components of the AR heterocomplex and appear to have interactions with AR in prostate cancer cells." (PMID 35805135, 2022).
prostate carcinoma (continued). "In the process of developing drugs for the treatment of prostate cancer, research on targeting of the AR has led to the discovery of ARIs." (PMID 35447901, 2022). "This increased stability allows for increased levels of 3βHSD1 and higher levels of potent downstream androgens such as DHT that can go on to activate AR-sensitive tissues such as prostate and prostate cancers." (PMID 37435458, 2022). "Studies on the highly castration-sensitive patient-derived xenograft (PDX) model BM18 revealed that ADT enriches for a population of prostate cancer cells with both stem-like and luminal characteristics and low AR expression." (PMID 35909568, 2022). "In case of prostate cancer, most cancer cells show enhanced AR expression, and AR-driven gene expression enhances β-oxidation of fatty acid (FA) to supply energy source and ATP, and finally, reduces glucose consumption of tumor cells." (PMID 36178912, 2022). "In conclusion, the present study revealed the interaction between TPX2 and AR in regulating the proliferation of prostate cancer cells." (PMID 35444697, 2022). "In this study, we combined immunostaining and bulk and single-cell transcriptome analyses to better characterize the status of AR in prostate cancer with neuroendocrine differentiation." (PMID 36033483, 2022). "NSUN2 stabilizes AR mRNA through cluster 5‐methylcytosine modification and activates a positive feedback loop to promote prostate cancer." (PMID 36169095, 2022). "In vivo studies utilizing the murine prostate cancer model TRAMP demonstrated the potential of DNA methyltransferase inhibition for the treatment of prostate cancer and AR reactivation." (PMID 35909568, 2022). "Emerging evidence suggests that the WNT signaling pathway, as well as FGF signaling, are among the AR-independent mechanisms of resistance involved in progression to NE or SCC prostate cancer." (PMID 35740556, 2022). "Prostate cancer growth and progression are sustained by AR signalling, hence androgen deprivation therapy is the gold standard treatment in PCa." (PMID 36111296, 2022). "Although the androgen receptor status represents a good predictor of response to androgen deprivation therapy, prostate cancer frequently becomes resistant to this approach and spreads." (PMID 35222290, 2022). "Each siRNA/RBD-S19-TAT protein complex was added to HeLa cells or prostate cancer-derived LNCaP cells that highly expressed AR, and the amount of CSK or AR mRNA was quantified by RT–qPCR." (PMID 36303212, 2022). "AR signalling is critical for normal prostate development but also drives prostate cancer cell growth and survival." (PMID 35702041, 2022). "For instance, Wnt3a has previously been shown to enhance AR-mediated transcription in LNCaP prostate cancer cells in vitro, leading to enhanced cell growth and colony formation." (PMID 35204808, 2022). "HC-1119 is a new second-generation AR antagonist that has been used in clinical trials to treat prostate cancer." (PMID 35960413, 2022). "As the field of prostate cancer continues to elucidate the complex relationships between taxane-induced microtubule dysfunction and AR signaling, the role of estrogen and estrogen receptors (ER) on taxane-induced microtubule dynamics is less clear." (PMID 35884386, 2022). "The capability of tumors to preferentially shuttle AR through nuclear transport is thought to contribute to taxane resistance in prostate cancer." (PMID 35884386, 2022). "AR has been shown to be a mediator of radioresistance in prostate cancer, and inhibition of AR with apalutamide results in an increased radiosensitivity through a decrease in non-homologous end-joining (NHEJ) efficiency." (PMID 35618789, 2022). "Acquired resistance was overcome by alternating SPA with the AR inhibitor enzalutamide, which induced adaptive upregulation of AR and resensitized prostate cancer to SPA." (PMID 36194476, 2022).
prostate carcinoma (continued). "Additional experiments have revealed that AR signaling plays a significant role in autophagy induction and prostate cancer progression." (PMID 35317831, 2022). "On the basis of its role in histone H4K16 acetylation, MOF serves as co-activator of nuclear factor–κB and androgen receptor for upregulating their transactivation capacity in prostate cancer." (PMID 36212422, 2022). "PROTAC 10 was effective in inducing AR degradation at concentrations lower than 1 nM in LNCaP and VCaP prostate cancer cell lines with a 24 h treatment time and was capable of achieving complete AR degradation in these cell lines." (PMID 35702041, 2022). "Next, we explored a potential relationship between PKCα and AR expression by analyzing eight prostate cancer datasets." (PMID 36818489, 2022). "They showed that the outcomes were slightly less than in the D-E group in AFFIRM (50% PSA decrease: 54%, the median PFS: 8.3 months), revealing the heterogeneity of prostate cancer in terms of AR signaling addiction and drug resistance." (PMID 35250590, 2022). "Conditional expression of human AR transgene in mouse prostatic Osr1-lineage cells results in HGPIN and prostatic adenocarcinomas as mice progressed in age10, recapitulating the oncogenic role of the AR as observed in human prostate cancer." (PMID 35902588, 2022). "The AR protein levels in LnCaP cells, an important pathway of androgen-dependent prostate cancer, decreased dramatically after heat treatment." (PMID 35453310, 2022). "By using immunostaining and bulk and single-cell transcriptome sequencing, we analyzed the AR status in prostate cancer with neuroendocrine feature to characterize the role of AR and AR signaling in neuroendocrine differentiation." (PMID 36033483, 2022). "In prostate cancer cell lines (LNCap DuCaP and VCaP), galiellalactone strongly repressed IL-6-induced activity of the androgen receptor (AR; e.g., PSA expression)." (PMID 36429126, 2022). "Androgen receptor (AR) is widely described as an androgen‐dependent transcription factor that plays a critical role during the natural history of prostate cancer." (PMID 34919781, 2022). "Substantial investigations have uncovered modifications in the androgen receptor pathway as a common form of treatment resistance in prostate cancer." (PMID 36317631, 2022). "We apply these methods to a novel model of castration-resistant (ENZ-sensitive) and ENZ-resistant PCa which we developed from the well-known AR-positive VCaP prostate cancer cell line." (PMID 36348939, 2022). "In prostate cancers, the transcriptional splicing variants of the AR gene have been linked to castration-resistance of prostate cancer after ADT and anti-AR therapy with Enzalutamide and Abiraterone." (PMID 35372068, 2022). "One aspect of AR biology that is most likely involved in prostate cancer is the complicated functional interplay between AR and epigenetic enzymes, including histone deacetylases (HDACs) and lysine demethylases (KDMs)." (PMID 34986150, 2022). "PIP5K1α promotes prostate cancer cell survival and invasion through regulation of expression of AR in PCa cells." (PMID 34932854, 2022). "Our data indicate that growth inhibitory concentrations of metformin regulate not only AR signaling but also other pathways critical for the survival of human prostate cancer cells." (PMID 36175875, 2022). "Androgen receptor (AR) is essential for prostate development and function, and also for prostate cancer (PCa) cell survival and proliferation." (PMID 34919781, 2022). "The findings of this study suggested the necessity for clinical trials to test artesunate in combination with androgen receptor antagonists in castrate-resistant prostate cancer patients." (PMID 35267408, 2022). "Androgen receptor (AR) signaling is an important survival pathway for castration-resistant prostate cancer (CRPC) cells." (PMID 36289357, 2022).
prostate carcinoma (continued). "IGF-1 is also implicated in castration-resistant PCa and has been shown to activate androgen receptor (AR) signaling in prostate cancer cells via the IGF-1R-forkhead box protein O1 (FOXO1) signaling axis." (PMID 35370981, 2022). "Given the abundant evidence supporting the role of epigenetic and chromatin regulators in prostate cancer progression, we strove to summarize how a few of these key players converge on the AR cistrome and the AR transcriptome in this review." (PMID 36212399, 2022). "It is interesting to point out, however, that AR is known to upregulate the expression of p21CIP1, a well-known inhibitor of cyclin-dependent kinases, in prostate cancer cell lines, including the ones tested in this study." (PMID 35204688, 2022). "Apart from AR mutation, AR variants such as ARV7 were also reported for resistance development and support androgen-independent growth of prostate cancer cells." (PMID 35800367, 2022). "We previously reported that ERG subtypes of prostate cancer have altered androgen receptor signaling, similar to the ETV4 subtypes of prostate cancer shown in the current study." (PMID 36289913, 2022). "How to overcome AR alternation during anti-androgen therapy is an enduring topic in prostate cancer resistance research." (PMID 36362304, 2022). "Unfortunately, prostate cancer cells eventually develop the ability to activate AR independently of androgen and patients invariably develop the more aggressive castration-resistant prostate cancer (CRPC), which is associated with a much worse prognosis." (PMID 34986150, 2022). "Androgen receptor (AR) is involved in the effect of androgen on tumor initiation and plays a major role in the recurrence and outcome of prostate cancer." (PMID 35637953, 2022). "A cell-culture study using the AR-positive prostate cancer cell line, LNCaP, suggested that CBD (up to 15 μM) was successful at initiating the apoptosis of cancer cells and acting as an antiproliferative agent." (PMID 35741337, 2022). "Our data support the consideration of GZ17-6.02 as a possible therapeutic agent in patients with AR+ prostate cancer." (PMID 36408163, 2022). "Dacinostat (LAQ824), a close analog of panobinostat, suppressed the Hsp90 client protein AR in LNCaP prostate cancer cells by an increase of acetylated Hsp90 levels accompanied by Hsp90-AR dissociation and AR decomposition." (PMID 35582529, 2022). "Mass spectrometry-based proteomic analysis of the VCaP prostate cancer cells treated with androgen and the androgen receptor (AR) signaling inhibitor darolutamide revealed a generally good agreement with transcriptomic responses." (PMID 36611998, 2022). "Surprisingly, important roles of AR and ER in the etiological factors of breast cancer and prostate cancer have been discovered, respectively." (PMID 36142861, 2022). "The importance of AR in prostate cancer development and progression makes it a major target for prostate cancer treatment." (PMID 36446767, 2022). "The degrader 137 (WWL0245) also showed good antiproliferative activity in BETi-sensitive cancer cells (including AR-positive prostate cancer cells) with an IC50 of 3 nM in MV4-11 cells." (PMID 35680848, 2022). "Androgen and androgen receptor (AR) targeted therapies are the main treatment for most prostate cancer (PC) patients." (PMID 35413990, 2022). "Due to the signaling role of AR in prostate cancer progression, KDM4B should have a critical role in this malignant tumor." (PMID 35317831, 2022). "In prostate cancer, the tumor stroma is enriched in CAFs that secrete androgen receptor (AR)-activating factors, which modulate AR signaling in cancer cells after androgen deprivation therapy." (PMID 35488263, 2022). "The androgen receptors (AR)–miR-34a interaction has been demonstrated previously in renal cell carcinoma and prostate cancer." (PMID 35625530, 2022).
prostate carcinoma (continued). "PC-3 cells are considered highly relevant cellular models for the study of advanced prostate cancer, as they lack AR expression and androgen-independent proliferation." (PMID 36348374, 2022). "Epigenetic reprogramming of the androgen receptor (AR) has been identified as an important process driving prostate cancer (PCa) progression." (PMID 36450752, 2022). "Our experimental approach considered the impacts of microenvironmental hypoxia in modulating the AR signaling pathway in prostate cancer cells." (PMID 35302608, 2022). "Hormone therapy that targets the androgen receptor (AR) remains the mainstay therapy for prostate cancer." (PMID 36035209, 2022). "A link between AR and NF-κB signaling is also indicated by the fact that androgen-independent prostate cancer cell lines and xenografts often exhibit an elevated constitutive NF-κB activity." (PMID 36551650, 2022). "The Androgen receptor plays an indelible role in the development and progression of prostate cancer, therefore, targeting androgen metabolism and androgen receptor are always the theme of treatment." (PMID 36439479, 2022). "The regulation of these genes shed light onto the importance of dual-modified AR in prostate cancer and feasibility of (R)-9b as a desirable therapeutic modality." (PMID 35704598, 2022). "For this reason, selective estrogen receptor modulators (SERMs), such as raloxifene, have been tested in AR-(PC3, DU-145) and AR+ (LnCaP) prostate cancer cells inducing apoptosis at micromolar concentrations." (PMID 35453603, 2022). "TR3 increases the androgen independence of AR signaling in prostate cancer cells by controlling AR expression, splicing events, and androgen-independent function and also stimulates tumorigenesis of prostate cancer cells." (PMID 35454821, 2022). "Phosphorylation at particular sites and enrichment of growth factors reactivate AR, which further increases prostate cancer proliferation under low androgen levels." (PMID 35800367, 2022). "Considering that AR plays a key role in prostate cancer, the possibility that tangeretin can synergize with sorafenib to reduce the expression of AR was assessed." (PMID 35111229, 2022). "The androgen receptor (AR) plays a complicated, yet vital, role in the normal function of the prostate, as well as in the progression of prostate cancer." (PMID 35741337, 2022). "More importantly, the combination of two compounds, a P2Y1 receptor agonist and an androgen receptor inhibitor, is found to be a potential combinatorial drug to overcome prostate cancer." (PMID 35129730, 2022). "Anyway, berberine induced cell apoptosis and inhibited cell proliferation in prostate cancer cell lines via suppressing androgen receptor signaling pathway." (PMID 35889396, 2022). "In this line, previous studies have shown that CAFs express functional AR and play a role in the development and progression of prostate cancer." (PMID 35885510, 2022). "Similar to olaparib, rucaparib was approved by the FDA—but not by the EMA—for the treatment of metastatic castration-resistant prostate cancer patients with germline and/or somatic BRCA1/2 mutations, who progressed on AR signaling inhibitor or taxane." (PMID 36010882, 2022). "In the present study, a bioactive peptide-rich SPH potentiated the antiproliferative activity of the competitive AR antagonist bicalutamide in two in vitro prostate cancer models." (PMID 35447901, 2022). "So, to get insight into key issues involved in AR transcriptional repressive activities in advanced prostate cancer, we decided to further focus on biological and/or molecular signatures associated with our lists of deregulated genes." (PMID 34919781, 2022). "It is well established that Brg1 is an essential effector for the regulation of PCa28,29, and AR is commonly recognized as a key driver of prostate cancer, even CRPC3." (PMID 35233061, 2022).